MMP9 (matrix metallopeptidase 9)
Diseases named in the same sentence as MMP9 in open-access papers (continued):
Sharing a sentence is not in itself a finding about the gene and the disease.
melanoma (continued). "Matrix metalloproteinases, especially MMP-2, MMP-9 and MT1-MMP (also named MMP-14), are largely involved in extracellular matrix degradation and melanoma cell migration." (PMID 22539938, 2012). "Endothelin B-receptor (ETB-R) is overexpressed in human melanoma, activation of the ETB-R pathway increases the expression of MMP-2 and MMP-9 and ETB-R antagonist induced an inhibition of tumor growth and a decrease of vascular density." (PMID 24281035, 2010). "In melanomas, higher levels of MMP-1, MMP-2, MMP-9, and MMP-14 have been observed in the more invasive and metastatic tumors." (PMID 20843370, 2010). "Consistent with these in vitro results, the expression of transcripts coding MMP-2, MMP-9, and TNF-α is similarly inhibited in the melanoma tumors recovered from HB-19 treated RET mice." (PMID 20573279, 2010). "With melanoma cells, we found that the areas of greatest macrophage density were peritumoral, and using a suitable in vitro model we demonstrated that upon contact with melanoma cells, inflammatory macrophages express increased levels of COX-2, uPAR and MMP-9." (PMID 20822533, 2010). "Thalidomide promoted B16F10 melanoma cell necrosis and inhibited VEGF, NF-κB, PCNA, MMP-2 and MMP-9 expression." (PMID 18983651, 2008). "Thereafter, increased mRNA levels of MMPs were reported in TCDD-treated human cells, such as, MMP1 in keratinocytes and melanoma cells, MMP2 in melanoma cells, MMP3 and MMP7 in endometrial cells, and MMP9 in prostate cancer cells and melanoma cells." (PMID 16704738, 2006). "MMP-3 and MMP-9 were completely absent.Melanoma: All three MMPs were highly expressed, exhibiting intense cytoplasmic and nuclear localization." (PMID 42158425, 2026). "Furthermore, dioscin decreased the secretion of MMP‐2, MMP‐9 and VEGF from melanoma cells treated with dioscin." (PMID 41546170, 2026). "Our findings demonstrate, for the first time, that five newly synthesized vemurafenib analogs—RF-86A, RF-87A, RF-94A, RF-94B, and RF-96B—effectively reduce the viability of A375 human melanoma cells and inhibit metastatic potential through suppression of MMP-2 and MMP-9 activity." (PMID 40872552, 2025). "14,15-EET induces G-CSF/IL-6 production in vivo, enhancing STAT3 activation in neutrophils to promote MMP-9 expression and suppress TRAIL expression, with neutrophil-derived MMP-9 being essential for inducing angiogenesis in dormant micrometastases in melanoma." (PMID 40564191, 2025). "By suppressing MMP-2 and MMP-9 activity in HCT116 cells (human colorectal adenocarcinoma), SK-MEL-5 cells (malignant melanoma), and MDA-MB-231 cells (breast adenocarcinoma), laminaran sulphate, which is extracted from the brown alga Fucus evanescens, was shown to be an effective anti-migratory drug." (PMID 41321380, 2025). "To further understand how CXCL13 enhances the invasiveness and immune evasion capabilities of melanoma cells, we examined the protein levels in melanoma cells after CXCL13 treatment and observed a significant upregulation of matrix metallopeptidase 9 (MMP9) and programmed death‐ligand 1 (PD‐L1)." (PMID 40692663, 2025). "Melanoma-derived exosomal miR-155 downregulates suppressor of cytokine signaling 1 (SOCS1), an inhibitor of the JAK2/STAT3 pathway, activating JAK2/STAT3 signaling, promoting MMP-9 expression, and enhancing tumor angiogenesis." (PMID 40284474, 2025). "In the context of melanoma, Th17-cells may contribute to tumor angiogenesis through the regulation of vascular endothelial growth factor (VEGF) and matrix metalloproteinase 9 (MMP9)." (PMID 40725022, 2025). "In line with the increased MMP9 expression around the tumor vasculature, a substantial reduction in the deposition of the ECM proteins fibronectin and collagen IV was observed in the perivascular region of HCmel12 melanomas in CD93–/– mice." (PMID 38441970, 2024).
melanoma (continued). "The dynamic control of MMP-9-dependent H3NT proteolysis, mediated by p300/CBP-induced H3K18ac, significantly contributes to the efficient transcription of MMP-9 responsive genes in melanoma cells." (PMID 39409117, 2024). "Additionally, luteolin inhibited proliferation, invasion, and metastasis in A375 melanoma cells by downregulating MMP2 and MMP9 and upregulating TIMP-1 and TIMP-2 expression levels." (PMID 40066127, 2024). "This MMP‐9‐dependent H3NT proteolysis constitutes a crucial process for driving pro‐osteoclastogenic and pro‐melanomagenic transcription programs, thereby promoting osteoclast differentiation and melanoma development." (PMID 38600695, 2024). "As a matter of fact, in the present paper, we demonstrate that TDO inhibition, but not IDO1 inhibition, significantly reduced MMP-9 activity of melanoma cells co-cultured with endothelial cells." (PMID 38794128, 2024). "MMP-9 expression was found exclusively in the horizontal growth phase of melanoma, not in the vertical phase, demonstrating that MMP-9 expression is a precursor to melanoma development." (PMID 38791873, 2024). "However, our recent studies with much greater attention to its nuclear function revealed that MMP‐9 can cleave H3NT to establish active transcription states during osteoclast differentiation and melanoma development." (PMID 38600695, 2024). "Given the established role for MMP‐9 in catalyzing H3NT proteolysis in osteoclast and melanoma cells, the positive correlation between H3NT cleavage and MMP‐9 expression levels in colon cancer cells suggests a potential involvement of MMP‐9 in H3NT clipping process." (PMID 38600695, 2024). "In studies using mice lacking MMP-9, there was a notable reduction in metastatic colony formation from melanoma and carcinoma cells." (PMID 38374934, 2024). "By targeting MMP9, MMP12, MMP14, and MMP16, it is conceivable that Estradiol and Calcitriol could disrupt critical pathways involved in melanoma progression, offering a novel and potentially effective approach for combating this aggressive form of skin cancer." (PMID 39493455, 2024). "Moreover, melanoma cells upregulate the pro-inflammatory activities of neutrophils as well as the expression of tumor-promoting factors, such as MPO, MMP-9 and NETs." (PMID 37525065, 2023). "MMP-9, as well as MMP-1, is a pro-angiogenesis factor, and they could both be prognostic biomarkers for melanoma." (PMID 36980564, 2023). "In addition, MMP9 plays a crucial role in melanoma cell metastasis and invasion through CD147/NFAT1/MMP9 pathway." (PMID 36793711, 2023). "The observed role of MMP-9 has potential therapeutic implications since treatment with MMP-9 inhibitor can restore a silencedstate of aberrantly activated genes and exert antagonistic effects on melanoma formation." (PMID 37293029, 2023). "Notably, MMP-9 inhibition blocked formation of pillars in vessels, and the inhibition of MMP-9 promotes abrogated pillar formation in melanoma, leading to suppression of angiogenesis in melanomas." (PMID 36980564, 2023). "The globular phenotype in LoVo-R cells, which in melanoma was considered a potential ameboid migrating one also secreting high level of MMP-9, could be related to the higher expression of MMP-9 measured in thicker Matrigel and highly concentrated collagen." (PMID 36551219, 2022). "To conclude, the increase of PCDH9 could suppress melanoma cells by observing the deregulation of MMP2, MMP9, and RAC1." (PMID 36452505, 2022). "Laminaran sulfate isolated from the brown alga Fucus evanescens was shown to be a potent anti-migratory agent by inhibiting MMP-2 and MMP-9 activity in human colorectal adenocarcinoma (HCT116 cells), malignant melanoma (SK-MEL-5 cells), and breast adenocarcinoma (MDA-MB-231 cells)." (PMID 35621924, 2022). "Hence, MMP2 and MMP9 were chosen as tumorigenic indicators to exhibit the correlation between PCDH9 and melanoma suppression." (PMID 36452505, 2022).
melanoma (continued). "Malyarenko and colleagues (2019) also conducted a study that demonstrated for the first time the ability of sulfated laminaran from the brown alga Dictyota dichotoma to significantly increase the inhibitory effect of X-rays on SK-MEL-28 melanoma cell migration by regulating MMP-2 and MMP-9 activity." (PMID 35621924, 2022). "In vivo study suggests that kaempferol has shown inhibitory activity against metastasis of murine melanoma B16F10 cells and could downregulate the expression of matrix metalloproteinase-9 (MMP-9) and its activity." (PMID 35883653, 2022). "In melanoma, metformin has been found to inhibit cancer cell invasion, proliferation, and epithelial–mesenchymal transition through the activation of AMPK and the inhibition of MMP2 and MMP9 expression." (PMID 36139556, 2022). "The pharmaceutical actions of Rg3 on the inhibition of MMPs were: MMP2 in six cell lines (originated from lung, thyroid, nasopharynx, colorectum, and bone tumor), MMP9 in four cell lines (lung, thyroid, nasopharynx, and bone tumor), and MMP13 in the B16F10 melanoma cell line, respectively." (PMID 36012338, 2022). "Therefore, we have chosen MMP2, MMP9, Pyk2, and Cyclin D1 as tumor metastasis indicators to explore the mechanism of how PCDH9 and RAC1 act on melanoma." (PMID 36387162, 2022). "Thus, our results indicate that, at least in part, both PARP-1 and MMP-9 are inhibited by DPG action, leading to abolishing melanoma cell migration." (PMID 35806253, 2022). "Our results show that melanoma CD248 contributes to cell migration and VM in part through modulating cell-ECM adhesion and MMP9 expression, which could promote tumor metastasis." (PMID 36401329, 2022). "Furthermore, it was indicated that the increased cell proliferation, migration, and invasion arising under the influence of adipocytes-conditioned medium was connected to the elevated activity of matrix metalloproteases MMP9 and MMP2 in melanoma cells." (PMID 33430277, 2021). "Similarly, IL-33 affects the progression of malignant melanoma cells by binding to its receptor ST2 and inducing tumor cell proliferation, migration, and invasion through MMP-2, MMP-9, and ERK1/2 phosphorylation." (PMID 33466236, 2021). "For example, TAMs upregulate urokinase-type plasminogen activator (uPAR) and secrete MMPs, such as MMP-9, which enable the remodelling of the ECM and increase the invasiveness of melanoma, or they upregulate such factors in melanoma cells through the secretion of TNFα and IL-1α." (PMID 34830780, 2021). "Thus, it is expected that ASE has an anticancer effect on melanoma and an inhibiting effect on melanoma invasion and metastasis through the reduction of the expressions of VEGF, MMP-2, and MMP-9, which are secreted during metastasis." (PMID 35011253, 2021). "Overall, our results demonstrated that ASE inhibited the growth and migration of B16-F0 cells through downregulation of the VEGF, MMP-2, and MMP-9 genes expression, which indicates ASE could be applied for the prevention and treatment of melanoma." (PMID 35011253, 2021). "MMP-9 (gelatinase B), similar to MMP-2, is present in melanoma both in tumor cells and stroma." (PMID 34360915, 2021). "In a variety of cells ranging from epithelial cells, macrophages, and CD4+ T cells to cells from tumors, such as myeloma, pancreatic cancer, and melanoma, membrane CD138 is cleaved by different proteinases, such as MMP9, MT1-MMP, MT3-MMP, collagenase, and trypsin." (PMID 34364875, 2021). "Recent reports have suggested that melanoma-derived factors could differentiate M2 macrophages that produce angiogenic factor such as VEGF and MMP9." (PMID 32707850, 2020).
melanoma (continued). "In RUNT KO melanoma cells, reduced expression of genes involved in metastatic processes (e.g., CD31, MMP9 and VEGFA) was observed, and genes involved in promoting bone metastasis, such as IBSP (coding for bone sialoprotein) and SPP1 (coding for osteopontin), were downregulated." (PMID 32204402, 2020). "It will particularly focus on Matrix Metalloproteinase 9 (MMP-9), in the degradation of ECM and the consequent progression of melanoma, as well as the potential therapeutic implication of both endogenous and exogenous MMP inhibitors for the design of new therapeutic protocols for melanoma patients." (PMID 32392801, 2020). "MMP-9 secretion has been associated with tumor dissemination, as MMP-9 was expressed only by cell lines derived from advanced-stage melanomas, whereas it was absent in cell lines derived from early-stage primary lesions." (PMID 32507967, 2020). "Moreover, JAK3 suppresses the migration and invasion of cultured melanoma cells by modulating the activities of matrix metalloproteinases 2 and 9 (MMP-2 and MMP-9)." (PMID 32051510, 2020). "In addition, exosomal miR-155 derived from melanoma cells upregulated the expression of proangiogenic factors, such as VEGF, FGF2, MMP9, in CAFs by targeting SOCS1/JAK2/STAT3 signaling pathway, which resulted in the increase of melanoma angiogenesis." (PMID 32489584, 2020). "MMP9 knockdown experiments corroborated these findings and showed that CAFs lacking the MMP-9 protease did not affect the PD-L1 level on the melanoma cell surface." (PMID 33171792, 2020). "The presence of keratinocytes, irrespective of contacts with melanoma cells, slightly augmented the MMP-9 mRNA levels in keratinocytes and sorely decreased TIMP-1 transcription in invasive melanoma cells." (PMID 32455575, 2020). "Our results indicated that curcumol attenuated the expression of MMP2 and MMP9; therefore, we sought to determine whether curcumol was responsible for regulating epithelial-mesenchymal transition(EMT) in mouse melanoma B16 cells." (PMID 32194780, 2020). "Similarly, luteolin has been found to reduce the proliferation, migration, and invasion of human melanoma cells by suppressing the expression of MMP-2 and MMP-9 and altering the PI3K/AKT signaling pathway." (PMID 32224968, 2020). "MMP9 expression is regulated by several pathways and epigenetic alterations; overexpression is due to the aberrant activation of the MAPK and AKT/mTOR signaling pathways almost always found in melanoma." (PMID 31623313, 2019). "MMP9 expression is regulated by several pathways and epigenetic alterations; overexpression can be the result of aberrant activation of the MAPK and AKT/mTOR signaling pathways almost always found in melanoma." (PMID 31623313, 2019). "Surprisingly, unlike SLNCR1, neither SLNCR2 nor SLNCR3 upregulate MMP9 or increase melanoma invasion, suggesting that SLNCR isoforms have at least partially unique functions." (PMID 31116991, 2019). "Recent studies based on mRNA and protein expression show that several MMPs, namely MMP-9, MMP-12 MMP-2, MMP-14, and MMP-19, play a role in melanoma aggressiveness and consequently may represent useful prognostic biomarkers." (PMID 30591049, 2018). "No significant percentage variations of MMP-9 serum levels were observed in melanoma patients at different times during the treatment with BRAF inhibitors (data not shown)." (PMID 30154717, 2018). "Our results demonstrated that bornyl cis-4-hydroxycinnamate is a potentially useful agent that inhibits melanoma cell migration and invasion, and altered melanoma cell metastasis by reducing MMP-2 and MMP-9 expression through inhibition of the FAK/PI3K/Akt/mTOR, MAPK, and GRB2 signaling pathways." (PMID 30042328, 2018). "Moreover, in a murine model of transplantable melanoma and fibrosarcoma, TANs are the main regulators of angiogenesis and tumor growth because of the expression of VEGF and MMP-9, suggestive of acquisition of a protumor phenotype." (PMID 29953504, 2018).
melanoma (continued). "The results indicate the combination of two inhibitors could induce MET in melanoma cells and decrease the expression of MMP-2/MMP-9." (PMID 28865485, 2017). "Inhibition of melanoma cell invasion by metformin is correlated with modulation of expression of proteins involved in epithelial-mesenchymal transition such as Slug, Snail, SPARC, fibronectin, and N-cadherin and with inhibition of MMP-2 and MMP-9 activation." (PMID 29245964, 2017). "A subsequent study from our group showed that MMP-2 and MMP-9 were not upregulated in invading melanoma cells but in the surrounding keratinocytes and fibroblasts." (PMID 27270229, 2016). "In addition to angiogenesis, under hypoxic conditions, HIF-1α plays an important role in the metastatic progression of melanoma by enhancing the expression of MMP such as MMP-2, MMP-9, and MMP-14." (PMID 27271600, 2016). "Moreover, nifuroxazide markedly impaired melanoma cell migration and invasion by down-regulating phosphorylated-Src, phosphorylated-FAK, and expression of matrix metalloproteinase (MMP) -2, MMP-9 and vimentin." (PMID 26830149, 2016). "The aim of this study was to evaluate clinical utility of vascular endothelial growth factor (VEGF), matrix metalloproteinase 2 (MMP-2), MMP-9, tissue inhibitors of metalloproteinase 1 (TIMP-1), and YKL-40 in serum of melanoma patients at pathological stages I–III." (PMID 26002577, 2015). "The patients with melanoma in comparison with the reference group had significantly higher median concentrations of VEGF (399 vs. 94 pg/ml; p = 000.1), MMP-9 (741 vs. 415 ng/ml; p < 0.001), TIMP-1 (161 vs. 116 ng/ml; p < 0.001), and YKL-40 (59 vs. 43 ng/ml; p = 0.001)." (PMID 26002577, 2015). "In a previous study, we revealed that A-07, D-12, and T-22 melanoma cells cultured at acidic extracellular pH show increased secretion of MMP-2 and MMP-9, enhanced invasiveness in vitro, and enhanced potential to develop experimental pulmonary metastases in BALB/c nu/nu mice." (PMID 26667022, 2015). "Specifically, data suggest that MMP2 and MMP9 could be directly involved in BBB permeability and that brain invasion by melanoma cells could be related to the overexpression of many MMPs." (PMID 25692137, 2015). "MMP-9 is an acidic pHe-signal target gene, with the acid-induced level of MMP-9, but not MMP-2, expression positively correlated with the metastatic potential of mouse B16 melanoma variants." (PMID 25493076, 2014). "Additionally, ursolic acid has been classified as a potent anti-angiogenic agent in melanoma, due to its inhibitory effects on the production of VEGF, MMP-2, MMP-9 and nitric oxide." (PMID 25102117, 2014). "Previously we showed that although the level of their expression does not correlate with invasive potential of melanoma variants, increased adhesion of highly invasive B16BL6 cells induced increased secretion of MMP9." (PMID 25180193, 2014). "A recent report on B16F10 melanoma cells showed that CSE1L overexpression triggered microvesicle generation, whereas CSE1L knockdown diminished Ras-induced microvesicle generation, MMP-2/MMP-9 secretion, and metastasis." (PMID 23369209, 2013). "By treating A-07, D-12, and T-22 human melanoma cells with media buffered to pH 6.8, several proteins such as MMP-2, MMP-9, cathepsin B, cathepsin L, VEGF-A, and IL-8 are upregulated and contribute to increased experimental lung metastasis post tail vein injections in athymic nude mice." (PMID 24367336, 2013). "DNE3 inhibited the motility and invasion of A2058 cell lines, and DNE3 clearly inhibited the secretion of MMP-2, MMP-9, and u-PA, thus indicating that DNE3 might have anti-invasive properties against a broad spectrum of melanoma cells." (PMID 21274459, 2011). "However, the mechanism responsible for selective inhibition of MMP-2, MMP-9 and TNF-α expression in HB-19 treated melanoma cells and tumors remains to be elucidated." (PMID 20573279, 2010).